KLF9 (KLF transcription factor 9)
Diseases named in the same sentence as KLF9 in open-access papers (continued):
Sharing a sentence is not in itself a finding about the gene and the disease.
melanoma (9 papers, 2019 to 2025). A malignant, usually aggressive tumor composed of atypical, neoplastic melanocytes. "The association observed between miR-378a-5p and KLF9 expression in the present study also raises the possibility that the latter could influence the invasive behaviour of melanoma cells through its effect on uPAR, VEGF or MMP42." (PMID 32060259, 2020). "High expression of both KLF9 and IFNGR1 was significantly linked to favorable overall survival outcomes in melanoma, as demonstrated by Kaplan–Meier analysis, indicating their possible protective roles similar to WTAP." (PMID 41301778, 2025). "Through further exploration of public databases, we identified KLF9 as a potential target gene through which WTAP exerts its effects in melanoma." (PMID 41301778, 2025). "The results showed a significant decrease in m6A enrichment on KLF9 transcripts upon WTAP knockdown in melanoma cells, suggesting that WTAP is required for maintaining the m6A modification of KLF9." (PMID 41301778, 2025). "Functional rescue experiments confirmed that WTAP inhibits melanoma cell proliferation and migration at least in part through upregulating KLF9." (PMID 41301778, 2025). "The migration ability of melanoma cells was parallel to cell proliferation when facing WTAP/KLF9 overexpression or knockdown." (PMID 41301778, 2025). "Experiments using adenovirus overexpression and siRNA technologies were conducted to assess the role of KLF9 in melanoma cells’ response to paclitaxel treatment." (PMID 37111314, 2023). "Our data suggested that paclitaxel selectively reduced cell viability and upregulated KLF9 expression in malignant melanoma cells." (PMID 37111314, 2023). "We used adenovirus overexpression and siRNA technologies to assess the role of KLF9 in mediating the response of malignant melanoma-derived cell lines RPMI-7951 and A375 to paclitaxel treatment." (PMID 37111314, 2023). "Taken together, data collected from the tested malignant melanoma cell models confirmed that KLF9 overexpression potentiated the anti-proliferative effects of chemotherapeutic agents in malignant melanoma cell lines." (PMID 37111314, 2023). "Downregulation of KLF9 was also confirmed when we compared the levels of KLF9 protein in primary melanocytes versus malignant melanoma cell lines and observed the significant reduction in RPMI-7951 and A375 cells." (PMID 37111314, 2023). "The role of KLF9 on paclitaxel-induced reduction in cell viability in malignant melanoma cell lines was further assayed using the MTT test." (PMID 37111314, 2023). "Herein, we demonstrated that paclitaxel treatment increased the mRNA and protein levels of KLF9 in malignant melanoma cell lines." (PMID 37111314, 2023). "This strengthens our hypothesis that the tumor-suppressive function of WTAP in melanoma is, at least in part, mediated by its role as an m6A “writer” on KLF9 mRNA." (PMID 41301778, 2025). "Given that KLF9 itself has been implicated in restraining malignant phenotypes in various cancers, including melanoma, this WTAP-KLF9 axis offers a novel mechanistic link between m6A regulatory machinery and melanoma suppression." (PMID 41301778, 2025). "Although our rescue experiments demonstrated that KLF9 overexpression counteracted the oncogenic effects of WTAP depletion, KLF9 is a multifunctional transcription factor that may regulate melanoma progression through WTAP-independent pathways." (PMID 41301778, 2025). "We propose that restoring levels of KLF9 may sensitize melanoma cells to the chemotherapeutic drug, paclitaxel." (PMID 37111314, 2023). "Thus, we investigated the role of KLF9 in paclitaxel treatment in two melanoma-derived cell lines systems, where KLF9 is knocked down in one and overexpressed in the other." (PMID 37111314, 2023). "In the literature, the role of KLF9 in melanoma progression is controversial." (PMID 37111314, 2023).
melanoma (continued). "We therefore used KLF9 overexpression and knockdown systems to determine the mechanism by which KLF9 affects paclitaxel-induced apoptosis and cell replication inhibition in melanoma cell lines." (PMID 37111314, 2023). "To explore whether paclitaxel regulates KLF9 expression, we treated primary melanocytes and malignant melanoma cell lines with 100 nM paclitaxel for 24 h." (PMID 37111314, 2023). "To investigate the effect of KLF9 overexpression or knockdown on cell proliferation and to study the response of paclitaxel’s anti-proliferative effects in malignant melanoma cells, we stained RPMI-7951 and A375 cells with the nuclear proliferation marker (Ki67)." (PMID 37111314, 2023). "Since Krüppel-like factor 9 (KLF9) (antioxidant repressor) is downregulated in melanoma, we propose that restoring KLF9 levels may sensitize malignant melanoma to chemotherapeutic agents, such as paclitaxel." (PMID 37111314, 2023). "Herein, we hypothesize that the KLF9-downregulation, seen in melanoma patients, may contribute to paclitaxel resistance." (PMID 37111314, 2023). "Interestingly, KLF9 downregulation is seen in various human cancers, including melanoma, and high KLF9 mRNA levels correlate with increased survival rates in melanoma patients." (PMID 37111314, 2023). "For example, the knockdown of KLF9 in cardiomyocytes protects them from ischemic injury, and a KLF9-dependent increase in ROS can result in cell death in lung tissues and induce proliferation of melanoma." (PMID 37737576, 2023). "KLF9 increased ROS regulating melanoma progression in a stage-specific manner." (PMID 36359788, 2022). "Also, KLF9 levels decrease during melanoma progression supporting a tumor suppressor function for KLF9-dependent ROS signaling at advanced stages of melanoma progression." (PMID 33091721, 2020). "By comparing BRAFV600Evs BRAFV600E/PTEN-/- mouse melanoma models, Bagati and colleagues elegantly showed that Klf9 deficiency does not affect primary tumor growth but it does promote melanoma metastasis." (PMID 33091721, 2020). "Similarly to other tumors, KLF9 also plays a protective role in melanoma." (PMID 41301778, 2025). "Thus, paclitaxel regulation of KLF9 is selective to malignant melanoma cells." (PMID 37111314, 2023). "Supplementary expression analysis revealed that KLF9 and IFNGR1—among the LASSO-selected genes—were consistently downregulated in melanoma samples compared to normal skin across multiple independent datasets, including TCGA and several GEO cohorts." (PMID 41301778, 2025). "Interestingly, it has been also shown that Nrf2 might amplify oxidative stress via induction of Klf9 making the regulation of Nrf2-Klf9-mediated response in the context of tumor and melanoma progression rather unclear and controversial to the common role of Nrf2." (PMID 33091721, 2020). "As anticipated, KLF9 also showed a negative correlation with the proliferative and migratory capabilities of melanoma cells." (PMID 41301778, 2025). "Upregulation of miR-378a-5p in M14 melanoma cells reduced both mRNA and protein levels of STAMBP, SP1, KLF9, FUS-1, and SUFU when compared with control transfected cells, while miR-378a-5p inhibition led to an opposite effect, upregulating the expression of target genes." (PMID 32060259, 2020). "For instance, a combination treatment with both paclitaxel as well as KLF9 overexpression could represent an effective treatment option for melanoma patients who are not candidates for immunotherapy or other targeted therapies." (PMID 37111314, 2023).
non-small cell lung carcinoma (9 papers, 2019 to 2025). A group of at least three distinct histological types of lung cancer, including non-small cell squamous cell carcinoma, adenocarcinoma, and large cell carcinoma. "For instance, in non-small cell lung cancer, decreased levels of KLF9 correlated with enhanced cell proliferation and invasion, suggesting that KLF9 functions as a tumor suppressor in this context." (PMID 40860800, 2025). "KLF7, KLF8, and KLF9 contribute to the progression of non-small cell lung cancer (NSCLC) and are the targets of some miRNAs." (PMID 35387557, 2022). "Moreover, hsa-miR-889-3p has been shown to target genes such as MNDA and KLF9 to promote cell growth and proliferation in osteosarcoma and non-small cell lung cancer, respectively." (PMID 39684278, 2024). "In non-small-cell lung cancer, KLF9 expression was downregulated in tumor tissues and cells and KLF9 could suppress the promotion effect of miR-141 on the progression on A549 cells." (PMID 34612136, 2021). "For instance, miR-889 expression was significantly up-regulated in non-small cell lung cancer cell lines and tissues, and miR-889 may play a potential therapeutic role in non-small cell lung cancer by targeting KLF9 to control the proliferation and migration of non-small cell lung cancer." (PMID 34116691, 2021).
ovarian carcinoma (9 papers, 2016 to 2025). A malignant neoplasm originating from the surface ovarian epithelium. "This indicates that although KLF9 is a tumor suppressor in most cancers, its high expression in ovarian cancer may be associated with tumorigenesis, but the mechanism still needs more research." (PMID 40860800, 2025). "Moreover, KLF9 inhibited Notch1 promoter activity in ovarian cancer cells and a loss of KLF9 expression in tumors was predictive of worse patient prognosis." (PMID 38067370, 2023). "Additionally, miR-600 expression was negatively associated with KLF9 expression in human ovarian cancer tissues." (PMID 35501825, 2022). "However, the expression of KLF9 was up-regulated in human ovarian cancer, and KLF9 deficiency significantly inhibited tumor growth in nude mice." (PMID 31024853, 2019). "In ovarian cancer (OC), KLF9 has been identified as a critical transcription factor that regulates tumor progression." (PMID 40860800, 2025). "In ovarian cancer, the shift of KLF9 from pro-survival in primary tumors to tumor-suppressive in metastases involves microenvironmental stresses (hypoxia/3D mechanical stress) inducing conformational changes and reorganization of cofactor recruitment." (PMID 40860800, 2025). "Its molecular interactions were determined through KEGG analysis, and real-time PCR-based expression analysis was performed to assess its co-expression with another oncogenic cellular pathway (miR-223, KLF9, and PKCε) proteins in ovarian cancer." (PMID 37833790, 2023). "TPD52, KLF9, PKCε, and miR-223 expression levels were compared between ovarian cancer patients and healthy controls." (PMID 37833790, 2023). "Overall, our data indicate that TPD52 and miR-223 are greater in ovarian cancer patients than in healthy persons, but the expression of KLF9 and PKCε is lower (0.2 ± 5.7) in ovarian cancer patients than in healthy individuals." (PMID 37833790, 2023). "The expression of genes TPD52, PKCε, KLF9, and miR-223 in the peripheral blood of ovarian cancer patients was studied in the present investigation, that indicated the expression of TPD52 as well as miR-223 were elevated." (PMID 37833790, 2023). "miR-600 promoted ovarian cancer cells stemness, proliferation and metastasis via downregulating KLF9." (PMID 35501825, 2022). "To investigate the downstream regulatory mechanism of miR-600 in ovarian cancer cells, we searched the TargetScan database and identified candidate KLF9." (PMID 35501825, 2022). "miR-600 promoted ovarian cancer cell stemness, proliferation and metastasis via downregulating KLF9." (PMID 35501825, 2022). "Consistent with this, levels of KLF9 and miR-600 expression were negatively correlated in human ovarian cancer tissues." (PMID 35501825, 2022). "Si-KLF9 partially abolished the discrepancy of self-renewal, growth and metastasis capacity between miR-600 knockdown ovarian cancer cells and control cells." (PMID 35501825, 2022). "As siRNA of KLF9 efficiently decreased the expression of KLF9, we then detected the effect of siRNA of KLF9 on the progression of ovarian cancer cells." (PMID 35501825, 2022). "For example, KLF5 encourages CSC viability in ovarian cancer, and KLF9 inhibits glioblastoma‐initiating stem cells." (PMID 33797839, 2021). "In ovarian cancer, the expression of KLF9 was abnormally up-regulated." (PMID 40860800, 2025). "For instance, in ovarian cancer, KLF9 exhibits heterogeneous expression in tissues." (PMID 40860800, 2025). "Three papers have described the disparate actions of KLF9 in ovarian cancer." (PMID 38067370, 2023). "However, two other papers demonstrated the opposite: that KLF9 overexpression inhibited the ‘stemness’ phenotype as well as proliferative and metastatic abilities of ovarian cancer cells." (PMID 38067370, 2023).
ovarian carcinoma (continued). "Moreover, KLF9 expression was considerably lower (0.61 ± 1.6) in ovarian cancer patients than in healthy controls, but the miR-223 expression was up-regulated (2.9 ± 4.0), and PKCε expression was reduced in ovarian cancer patients." (PMID 37833790, 2023). "Therefore, in present investigation, we determined the co-expression of TPD52, PKCε, KLF9, and miR-223 in ovarian cancer." (PMID 37833790, 2023). "In KLF9, expression levels in ovarian cancer were much lower than in healthy controls." (PMID 37833790, 2023). "For instance, reduction of KLF9 could facilitate stemness in ovarian cancer via Notch1/slug signalling." (PMID 37400979, 2023). "In conclusion, our results suggest that miR-600 promotes ovarian cancer cell stemness, proliferation and metastasis via directly downregulating KLF9, and impairing miR-600 levels may be a new treatment strategy for ovarian cancer in the future." (PMID 35501825, 2022). "Considering the important role of miR-600/KLF9 axis in ovarian cancer cells stemness, proliferation and metastasis, we believe that targeting the miR-600/KLF9 axis could be a novel therapeutic strategy for ovarian cancer." (PMID 35501825, 2022). "Next, we investigated the role of KLF9 in miR-600-mediated ovarian cancer cells progression." (PMID 35501825, 2022). "miR-600 regulated KLF9 expression and may therefore promote the progression of ovarian cancer." (PMID 35501825, 2022). "Moreover, the proliferation and invasive capacity of miR-600 knockdown ovarian cancer cells could be restored through interference of KLF9." (PMID 35501825, 2022). "Additional studies on the roles, pathways, and interactions of TPD52, KLF9, miR-223, and PKC may give valuable insights into the progression of ovarian cancer and assist in identifying novel therapeutic targets." (PMID 37833790, 2023). "Early response (6 hours) of A2780 ovarian carcinoma cells to SFN treatment involves generation of mitochondrial ROS and increased transcription of NRF2 and its downstream regulated genes including heme oxygenase 1, NAD(P)H:quinine oxidoreductase 1, and KLF9." (PMID 27528021, 2016). "Aligned with these potential tumor repressive actions of KLF9 are the findings that miR-600, which targets the 3′-UTR of KLF9 mRNA, is more highly expressed in ovarian cancers than in normal tissue, and elicited effects opposite to those of KLF9 in ovarian cancer cells." (PMID 38067370, 2023).
Obesity (8 papers, 2013 to 2025). Accumulation of substantial excess body fat. "The three-zinc-finger transcription factor Krüppel-like factor 9 (KLF9) has previously been linked to obesity and adipocyte differentiation." (PMID 35406507, 2022). "Moreover, Klf9 deficiency in mice alleviated high‐fat diet‐induced obesity and improved glucose intolerance and insulin resistance." (PMID 40717541, 2025). "Moreover, we identified the activation of KLF9 in macrophages as a mechanism underlying the anti-inflammatory effects and adverse metabolic outcomes of GCs, including obesity and weight gain." (PMID 38331933, 2024). "In East Asian populations, single-nucleotide polymorphisms (SNPs) in the human KLF9 gene are associated with obesity, however, the functional consequences of these KLF9 SNPs are unknown." (PMID 35406507, 2022). "Because IL-6, COX2/PGE2, and M2a macrophage activation have been proven to protect against obesity, our results indicate that the Klf9 transgene in macrophages promotes obesity by inhibiting M2a macrophage polarization and IL-6 and PGE2 secretion." (PMID 38331933, 2024). "We next examined potential mechanisms by which the myeloid-specific Klf9 transgene leads to obesity." (PMID 38331933, 2024). "We show that KLF9 in macrophages integrates the beneficial anti-inflammatory effects and adverse metabolic effects (including obesity and weight gain) of GCs." (PMID 38331933, 2024). "Obesity upregulated the expression of Klf2, Klf4, Klf6 and Klf9 at all timepoints in heart art, cap and ven ECs." (PMID 36400935, 2022). "Klf9 overexpression leads to macrophage deactivation and obesity." (PMID 38331933, 2024). "We used this model to evaluate the in vivo effects of Klf9 KO on obesity/adiposity and related parameters including hepatic lipid content, circulating adipokine concentrations, and hepatic and systemic oxidative stress, all of which are considered to positively influence HCC risk." (PMID 35406507, 2022). "Thus, we speculated that KLF9 directly affected the function of macrophages, thereby promoting obesity." (PMID 38331933, 2024). "Targeting KLF9 in macrophages could be a strategy to treat obesity and metabolic disease." (PMID 38331933, 2024). "Moreover, myeloid Klf9 knockout largely blocks obesity induced by chronic GC treatment." (PMID 38331933, 2024). "Furthermore, the myeloid-specific Klf9 transgene promotes obesity." (PMID 38331933, 2024). "For instance, in obesity models, NAT10 knockdown reduces ac4C modification on KLF9 mRNA, destabilizes its transcripts, and suppresses downstream CEBPA/B-PPARG pathway activity, thereby inhibiting adipogenesis and alleviating high-fat diet-induced obesity." (PMID 40588654, 2025). "Thus, KLF9 in macrophages may be therapeutically targeted to treat GC-induced obesity." (PMID 38331933, 2024). "To investigate whether GC-inducible KLF9 in macrophages promotes obesity, we generated Rosa26-Klf9flox/flox (R-loxP) mice with an insertion of the CAG-LoxP-Stop-Loxp-Klf9 cassette into the mouse Rosa26 locus (Klf9 knockin mice)." (PMID 38331933, 2024). "Utilizing an HFD-fed model of WT and Klf9 null mice, we showed that KLF9 represses hepatic and systemic oxidative stress and hepatic inflammation state, while having no overt effects on obesity/adiposity." (PMID 35406507, 2022). "Studies of obesity have shown highly comparable effects of common variants across major ancestry groups, strongly supporting shared common BMI and obesity loci across populations, although ancestry-specific loci have also been shown, such as KLHL32 in Africans and KLF9 in Asians." (PMID 28515345, 2017). "Thus, our results indicate that KLF9 in macrophages, rather than neutrophils in AT function, contributes to obesity." (PMID 38331933, 2024). "However, the in vivo effects, if any, of KLF9 on adiposity/obesity are not well documented." (PMID 35406507, 2022).
bladder cancer (7 papers, 2019 to 2023). "A case in point is that miR‐494‐3p is the upstream gene that represses KLF9 expression in bladder cancer." (PMID 37904708, 2023). "However, several studies have reported that circPTPRA upregulates KLF9 by sponging miR‐636 or interacting with IGF2BP1 to inhibit the progression of bladder cancer." (PMID 37041721, 2023). "In addition, hsa-miR-636 can promote the proliferation of bladder cancer cells by reducing the expression of Kruppel-like factor 9 (KLF9) on the 3’UTR of its mRNA." (PMID 36882772, 2023). "KLF9 expression was suppressed by miR-636 to enhance the proliferation of bladder cancer cells." (PMID 34612136, 2021).